EGFR (epidermal growth factor receptor)
Diseases named in the same sentence as EGFR in open-access papers (continued):
Sharing a sentence is not in itself a finding about the gene and the disease.
sarcoma (continued). "Expression of urokinase-type plasminogen activator receptor (uPAR) and epidermal growth factor receptor (EGFR) has been shown in sarcoma, with uPAR expressed in EWS and both EGFR and uPAR expressed in RMS." (PMID 31311607, 2019). "EGFR amplification was showed to be amplified in 25% of the patient samples and in 24% of the sarcoma cell lines." (PMID 30704460, 2019). "In this study, using a high-throughput drug screening method, we tested 12 HNSCC cell lines cultured on plastic, mouse sarcoma–derived Matrigel, or Myogel using 19 anticancer compounds targeting EGFR, MEK, and PI3K/mTOR." (PMID 31905951, 2019). "Flow cytometry was used to determine the expression of both EGFR and uPAR on pediatric sarcoma cells derived from RMS (RH30) and EWS (TC-71)." (PMID 29552283, 2018). "EGFR has been detected at varying levels in both cell lines and tumor samples of the three most common pediatric sarcomas, RMS, EWS and osteosarcoma (OS)." (PMID 29552283, 2018). "We also found in our 22 DFSP patients that EGFR expression increased with DFSP progression to high grade sarcoma, a known marker of poor prognosis." (PMID 29492209, 2018). "Urokinase-type plasminogen activator receptor (uPAR) and epidermal growth factor receptor (EGFR) are surface proteins expressed by some pediatric sarcomas." (PMID 29552283, 2018). "Their study indicated that targeted therapy that blocked EGFR (epidermal growth factor receptor)-RAS (rat sarcoma) pathway can be effective." (PMID 29560121, 2018). "We show for the first time that a de-immunized bispecific ligand toxin, EGFATFKDEL, directed against EGFR and uPAR, successfully targets pediatric sarcoma." (PMID 29552283, 2018). "While targeting EGFR has been widely explored in adult solid tumors, the effectiveness of EGFR targeting in pediatric sarcomas is less clear." (PMID 29552283, 2018). "The expression of epidermal growth factor receptor (EGFR) protein in metastatic sarcoma cell lines was first reported in 1998." (PMID 28556791, 2017). "Given the insufficient clinical efficacy of anti-EGFR therapy in sarcoma, our aim was to investigate the mechanism of gefitinib resistance and therapeutic combinations overcoming the resistance to improve the efficacy of targeted-therapies in sarcoma." (PMID 26909593, 2016). "Recent clinical trials indicated a potential for anti-angiogenic, anti-EGFR and immunotherapeutic approaches for patients with sarcomas, which led us to investigate these and other targetable pathways in malignant phyllodes tumor of the breast." (PMID 26625196, 2016). "Anti-tumour effects of Fx have also been investigated on xenografted sarcoma 180 in mice, resulting in significant growth inhibition with increased apoptosis as a result of epidermal growth factor receptor (EGFR)/Janus kinase (JAK)/STAT signalling disruption." (PMID 26264004, 2015). "They provided evidence that Spry2 is necessary for sarcoma formation by patient-derived fibrosarcoma cell lines or HRAS oncogene-transformed human fibroblasts through EGFR signaling." (PMID 24744103, 2014). "Previous studies showed that EGFR targeting combined with chemotherapy displayed marked antitumor activity against some sarcoma cell lines both in vitro and in vivo." (PMID 23056514, 2012). "EGFR gene expression is more common in SS compared with other sarcomas." (PMID 41155410, 2025). "Hence, EGFR+ and EGFR– sarcoma human xenografts were exposed to doxorubicin chemotherapy, radiation, or both." (PMID 37193364, 2023). "This lack of correlation may be due to the benign nature of oral lipomas since EGFR is overexpressed mainly in sarcomas." (PMID 37194849, 2023). "ABY-029 follows EGFR very closely in terms of staining sarcomas." (PMID 37193364, 2023).
sarcoma (continued). "Additionally, synthetic ligands targeting EGFR and uPAR effectively induced sarcoma cell death in vitro and suppressed tumor growth in vivo." (PMID 36258189, 2022). "Collectively, these studies provide a strong rationale for clinical translation of this BLT as adjuvant therapy to supplement standard of care therapies for treating both residual and metastatic, relapsed cancers, such as sarcomas, and potentially other EGFR- and uPAR-expressing cancers." (PMID 34771541, 2021). "Furthermore, a phase 0 study investigated ABY-029, an affibody targeting EGFR coupled to 800CW, for the resection of sarcomas." (PMID 34633509, 2021). "Enrichment analysis showed that neochlorogenic acid may act on haemopoietic cell kinase, epidermal growth factor receptor, sarcoma, etc., thus inhibiting HIV-1 infection." (PMID 34714196, 2021). "EGFR targeting is advantageous because it is a viable target for multiple tumors with diverse histological and developmental origins, including carcinomas, sarcomas, and brain tumors." (PMID 32630411, 2020). "In conjunction with our recent published data (activated EGFR is an independent prognostic factor for overall and/or cancer specific survival), these findings indicated that EGFR may be a promising anti-sarcoma target." (PMID 32002123, 2020). "Interestingly, specific therapies against NeuGcGM3 alone or combined with an anti-EGFR strategy showed promising clinical benefits in sarcoma patients." (PMID 31182063, 2019). "The remaining patients in this group (3/98; 3%) were sarcoma (GIST) patients with NF1 mutations indicating they should not receive imatinib, or NSCLC patients with EGFR T790M mutations (3/98; 3%) indicating resistance to first and second generation EGFR TKIs." (PMID 31384390, 2019). "In our DFSP patients, EGFR and STAT5a/b phosphorylation levels were correlated, suggesting that a similar STAT-mediated EGFR signaling could be involved DFSP evolution to high grade sarcoma." (PMID 29492209, 2018). "We thus demonstrated that in DFSP evolution to high grade sarcoma, EGFR and SNAIL were involved, with EGFR activation and signaling through TOR and STAT5a/b downstream effectors, which could lead on to new therapies for advanced DFSP." (PMID 29492209, 2018). "While prior efforts to block EGFR on pediatric sarcoma have had limited success in inducing tumor regression and preventing progression, we show that receptors that are selectively overexpressed on tumor cells can be used to deposit a pseudomonas exotoxin, leading to tumor cell death." (PMID 29552283, 2018). "Thus, we identified two pediatric sarcoma cell lines that express uPAR, but differed in EGFR expression, allowing us to test the relative benefit of dual antigen targeting vs. monospecific targeting with the bispecific immunotoxin EGFATFKDEL." (PMID 29552283, 2018). "Therefore, investigation of the activity of EGFR through pEGFR and its downstream signalling in sarcoma is needed for identification of predictive markers of patient survival and formulating future design of targeted therapy." (PMID 28556791, 2017). "It is likely that another oncogene such as v-erbB (a mutated version of epidermal growth factor receptor; EGFR) would be needed, as in AEV-induced erythroleukemia and sarcoma, to collaborate with TRα1PV to bring out the transformed phenotypes in erythroid cells of Thra1PV/+ mice." (PMID 28910278, 2017). "The over-expression of pEGFR, pAKT, pERK and pSTAT3 were found in sarcoma patients unrelated to histology, indicating EGFR-targeted therapy may benefit sarcoma patients." (PMID 26909593, 2016). "In addition, co-expression of both EGFR and NeuGcGM3 ganglioside (30-70 %) was observed in others tumors with small number of patients but of different origin as sarcomas (n = 3) and non-Hodgkin lymphomas (n = 3)." (PMID 27449755, 2016). "Early data suggest that blocking EGFR/HER1 by its specific inhibitor may have activity in sarcomas through tyrosine kinase signaling inhibition." (PMID 25674538, 2015).
sarcoma (continued). "In addition, EGFR was positively expressed in both cancerous and sarcoma components, indicating that targeting EGFR may be effective in inhibiting the proliferation of both carcinoma and sarcoma components." (PMID 35865143, 2022). "In mouse models containing sarcoma xenografts, the in vivo antitumor effect of eckol was shown not only due to its ability to interfere with the expression of caspase-3, caspase-9, Bcl-2 and Bax genes, but also due to its ability to inhibit epidermal growth factor receptor (EGFR) expression." (PMID 36547889, 2022). "Similarly, cetuximab has minimal activity in EGFR positive advanced sarcoma." (PMID 25674538, 2015). "EGFR signaling regulates cell motility through activation of EGFR's intrinsic kinases, leading to the activation of several downstream intracellular signaling pathways, including rat sarcoma–MAPK kinase (MEK), extracellular-related kinase (ERK), phosphoinositide 3-kinase (PI3K) and AKT pathways." (PMID 26515726, 2015). "However, in recent years data have accumulated that EGFR might also be hyperactivated in human sarcomas." (PMID 26526352, 2015). "In this review, we provide an update of the CAR T cell therapies that are currently being tested in pediatric sarcoma clinical trials, including those targeting tumors that express HER2, NY-ESO, GD2, EGFR, GPC3, B7-H3, and MAGE-A4." (PMID 34572932, 2021). "In this subtype of sarcoma, CDKN2A firmly connects to MDM2, CCND1, PIK3CA, CDK4, CBX7, and less firmly to EGFR, and IL-6." (PMID 34359782, 2021). "Consistent expression of EGFR and uPAR (PLAUR mRNA) was found across human sarcomas in the Cancer Genome Atlas (TCGA); similarly, both proteins were found to be expressed in a synovial sarcoma tissue microarray." (PMID 32630411, 2020). "Gliosarcoma, however, does not exhibit amplification or mutations of EGFR at the same frequency, suggesting there may be additional/alternate mechanisms propelling tumorigenesis and potentially mesenchymal transition into a sarcoma phenotype." (PMID 31073965, 2019). "Tyrosine kinases are highly expressed in sarcomas including EGFR and PDGFRA in SS, FGFR, and EGFR in ARMS, and upstream mediators of ERK1/2 in EwS." (PMID 31970591, 2019). "We studied here the possible involvement of EGFR expression and signaling in DFSP evolution to high grade sarcoma, using laser-microdissection and tissue-based molecular methods in a series of 22 patients." (PMID 29492209, 2018). "As EGFR expression in cancer may be linked to the epithelial-mesenchymal transition (EMT), and as EMT may impede the effect of EGFR-directed therapies, we analyzed the mRNA and protein expression of EMT factors in DFSP center, DFSP infiltrative periphery and DFSP-T higher-grade sarcoma areas." (PMID 29492209, 2018). "We also demonstrated similar patterns for EGFR and SNAIL expression in the areas of DFSP progression to high grade sarcoma." (PMID 29492209, 2018). "We first demonstrated that EGFR mRNA and protein are expressed by tumor cells in a majority of DFSP, preferentially in the areas of local extension and areas of higher-grade sarcoma transformation." (PMID 29492209, 2018). "In our cases, laser microdissection enabled us to localize EGFR phosphorylation in the areas of DFSP local extension and DFSP-T higher-grade sarcoma." (PMID 29492209, 2018). "Using the most current bioinformatics TCGA database, the expression on of EGFR and PLAUR on 212 human sarcomas was explored." (PMID 29218302, 2017). "In addition, no EGFR mutations were detected in our sarcomas, consistent with other series." (PMID 25906748, 2015). "Recently, epidermal growth factor receptor (EGFR) overexpression was observed in both CD and follicular dendritic cell (FDC) sarcoma, thus EGFR was suggested to be a connection between hyaline vascular CD and FDC sarcoma." (PMID 24649966, 2014).
sarcoma (continued). "Prominent pathway alterations, such as phosphoinositide 3-kinase (PI3K)/protein kinase B (AKT), epidermal growth factor receptor (EGFR), fibroblast growth factor receptor (FGFR), cell cycle protein-dependent kinases 4 and 6 (CDK4/6), and rat sarcoma (RAS) pathways, have been observed." (PMID 39544292, 2024). "This specific case is supported by e.g., public datasets for nine of the sarcoma lines used here, for which no oncogenic driver alteration has been found for EGFR or HER2 (Dataset EV1)." (PMID 38177929, 2024). "Therefore, STAP2 potentially regulates signaling pathways, such as EGFR/PIK pathway, inducing sarcomas." (PMID 35565213, 2022). "EGFR targeting has historically translated to poor outcomes in pediatric sarcoma patients and uPAR targeting had not been attempted before." (PMID 32630411, 2020). "There are a few published articles on synergism of arsenic-based drugs with EGFR inhibitors in cancer, but none in sarcoma models." (PMID 32002123, 2020). "For example, it was reported that the TKI dasatinib, but not EGFR-directed inhibition, decreased cell viability of sarcoma initiating cells in combination with doxorubicin." (PMID 32532153, 2020). "Alternatively, overexpressed surface targets that drive sarcoma biology (i.e., insulin-like growth factor type 1 receptor (IGF1R), EGFR) may provide additional candidates for a cancer vaccine or T cell therapy (i.e., CAR T cell)." (PMID 31311607, 2019). "Several papers have established the involvement of EGFR in ROR1-mediated survival signaling within carcinomas, which may not be able to explain why ROR1 is expressed the highest in the sarcoma and mesothelioma and predicts bad prognosis in these cancers." (PMID 31137681, 2019). "EGFR and ERBB2 activation in LNCaP cells under the influence of osteoblast-derived sarcoma cells (OHS) has been reported to activate EGFR/ERBB2 signaling pathways in LNCaP cells co-cultured with osteoblastic cells that had been differentiated from human mesenchymal stem cells or OHS cells." (PMID 31137764, 2019). "In all DFSP and DFSP-T samples studied, the EGFR/RNaseP allele ratio was in the normal range, indicating no significant EGFR allele gain or loss in DFSP center, DFSP infiltrative periphery, or DFSP-T higher-grade sarcoma." (PMID 29492209, 2018). "Here, we studied EGFR, another tyrosine kinase receptor, using laser-microdissection to select the different histologic components of DFSP (DFSP center, DFSP infiltrative periphery, DFSP-T higher-grade sarcoma), in 22 patients followed over 3 to 156 months." (PMID 29492209, 2018). "EGFR protein and mRNA were expressed in 13/22 patients with DFSP or DFSP-T, and increased with tumor progression, both in microdissected areas of higher-grade sarcomas and in microdissected areas of local extension." (PMID 29492209, 2018). "Furthermore, both the Cl2 and Cl3 subgroups, compared with the other four, showed an up-regulation of genes belonging to pathways involving tumor growth factor β (TGFβ), rat sarcoma (RAS), epidermal growth factor receptor (EGFR), and Cyclin D1." (PMID 25821127, 2015). "EGFR and E-cadherin were expressed in carcinomas, but not in sarcomas." (PMID 39268521, 2024). "EGFR was overexpressed in 22.6% of sarcomas but not in any of the benign lesions." (PMID 37194849, 2023). "In a mouse model of transplanted sarcoma, eckol derived from brown algae increases TUNEL-positive apoptotic cells via caspase-9/3 activation and down-regulates the expression of Bcl-2, Bax, and EGFR (epidermal growth factor receptor), as well as EGFR phosphorylation." (PMID 37760037, 2023). "EGFR was not overexpressed in adenoid cystic carcinoma and sarcoma samples." (PMID 38414930, 2023). "Considering the positive regulation of tumour energy production by both the EGFR signalling and tumour metabolism pathways, this study aimed to investigate the effect and mechanisms of combination therapy using gefitinib and PENAO in sarcoma cell lines in vitro and in vivo." (PMID 32002123, 2020).
sarcoma (continued). "Efforts to target EGFR in pediatric sarcoma have been attempted previously, with little success when translated to patients while uPAR has not previously been targeted in pediatric sarcoma." (PMID 29552283, 2018). "Our results suggest an important role for activation of the EGFR pathway in sarcoma biology that may be independent of histology." (PMID 28556791, 2017). "Our results demonstrated that combining dasatinib and doxorubicin decreases cell viability of a cell line less sensitive to doxorubicin treatment and that targeting EGFR may not be a future treatment strategy for sarcoma patient." (PMID 26788073, 2016). "EGFR activity enhances tumor growth, invasion, and metastasis, thus conferring a more aggressive phenotype, and further supporting the epithelial–mesenchymal plasticity model in patients with sarcoma: indeed invasion and dissemination in non-epithelial tumors could be due to EGFR expression on CTCs." (PMID 34063272, 2021). "Furthermore, the observations that EGF stimulation significantly increased protein expression of pAKT and pERK, but not pSTAT3, indicated that both AKT and ERK pathways in sarcomas may be mainly stimulated by EGF/EGFR activation." (PMID 26909593, 2016). "BEZ235 was studied because PI3K/mTOR signaling plays a critical role in sarcoma progression, and BEZ235’s inhibitory effects on cancer cell growth are independent of EGFR status." (PMID 40427168, 2025). "EGFR and PLAUR gene expression were detectable in 100% of samples regardless of sarcoma type with a variation in intensity." (PMID 29218302, 2017). "Interestingly, non-injection-site sarcomas did not exhibit immunohistochemical expression of PDGFR and EGFR." (PMID 37835664, 2023).